DCC (DCC netrin 1 receptor)
Diseases named in the same sentence as DCC in open-access papers (continued):
Sharing a sentence is not in itself a finding about the gene and the disease.
colon carcinoma (16 papers, 1997 to 2024). "The repulsive activity of Unc-5 on axon guidance is antagonized by frazzled (fra), which encodes the fly ortholog of mammalian deleted in colon carcinoma (DCC)." (PMID 37039476, 2023). "Dcc (or DCC, deleted in colon carcinoma) gene encodes a transmembrane protein, which acts as a receptor of neutrin-1, a key protein in axonal guidance and neuronal cell death induction." (PMID 36432096, 2022). "In colon cancer, deletion of DCC confers a survival advantage and underscores the dependence receptor concept." (PMID 39023520, 2024). "The DCC (deleted in colon cancer) subgroup of the immunoglobulin superfamily are ligands for netrin, with roles in the migration and guidance of axonal growth cones." (PMID 20346106, 2010). "In the present study the mRNA and protein expression and rearrangements at the DNA level of the DCC gene were addressed in 25 osteosarcomas and several tumour cell lines, including osteosarcoma- and colon carcinoma-derived cell lines." (PMID 9155051, 1997). "Reestablishment of DCC expression has been shown to suppress tumorigenicity, and hypermethylation of its promoter region has been detected not only in breast, gastric, and colon cancers, but also in oral squamous cell carcinoma." (PMID 38538728, 2024). "In the same vein, the Netrin-1/DCC guidance gene set, otherwise known as commissural axon pathfinding, contributes significantly to synapse formation and plasticity via two main components, Netrin-1 (ligand) and its receptor DCC (deleted in colon cancer)." (PMID 39000495, 2024). "In sporadic colon cancer tumorigenesis, the chronological sequence is loss of APC, aneuploidy, methylation, microsatellite instability, activation of K-Ras and COX-2, change in DCC/DPC4 genes and loss of function of p52." (PMID 34944856, 2021). "Commissural axons express the Netrin1 receptor DCC (deleted in colon cancer), and accordingly, mice mutant for either Netrin1 or DCC display severe axon guidance defects, in which many commissural axons fail to invade the ventral spinal cord and are unable to cross the midline." (PMID 23772206, 2013). "Indeed, DCC is generally down-regulated or deleted in colon cancer patients owing to its TSG properties which is more consistent with its deletion status using aCGH in our patients." (PMID 20126641, 2010). "Immunoblots of samples from 25 pairs of colonic cancers and adjacent normal tissues and from five adenoma tissues revealed that all normal colonic and adenoma tissues significantly expressed the DCC protein, whereas colonic cancer tissues showed poor expression." (PMID 9472645, 1998). "Increased expression levels of NTN1 and its receptor NEO1 in the visceral adipose tissue from patients with obesity and colon cancer together with elevated DCC and UNC5B mRNA levels in patients with colon cancer were found." (PMID 36831381, 2023). "In addition, colonic cancer patients with liver metastasis expressed significantly lower levels of DCC than those without, suggesting the prognostic value of DCC expression." (PMID 9472645, 1998).
depression (14 papers, 2018 to 2025). "Although these findings do not establish causality, animal studies using mouse models of depression have shown that increased DCC expression in the prefrontal cortex induces susceptibility to depression-like phenotypes." (PMID 40405979, 2025). "Depression risk gene DCC netrin 1 receptor (DCC) novel isoform Tx9 had significantly higher TPM in cerebellum." (PMID 40988056, 2025). "This knowledge brings to light the potential of DCC and its associated signaling pathways as prospective therapeutic targets for both obesity and depression." (PMID 40405979, 2025). "Further confirmation of the Netrin-1/DCC system as a depression risk marker comes from a recent study that integrated multi-omics data." (PMID 37035502, 2023). "There were 427 additional SNPs significantly associated with the expression of DCC (p < 0.05), and many of these SNPs also showed genome-wide significant associations with depression." (PMID 32184385, 2020). "Multiple depression risk genes are identified after combined investigation of integrative results, among which the netrin 1 receptor (DCC) gene is prioritized as a high-confidence candidate." (PMID 32184385, 2020). "These integrative analyses identify multiple high-confidence depression risk genes, and numerous lines of evidence supporting pivotal roles of the netrin 1 receptor (DCC) gene in this illness across different populations." (PMID 32184385, 2020). "The netrin 1 receptor (encoded by DCC) has been robustly associated with depression, schizophrenia and related traits." (PMID 30745170, 2019). "We identified RPL31P12, NEGR1, and DCC as common risk genes for obesity and depression." (PMID 40405979, 2025). "Additionally, the DCC gene is associated with major depressive disorder, schizophrenia, and bipolar disorders." (PMID 39452151, 2024). "Risk alleles correlated with brain DCC mRNA levels show robust link with the onset of depression." (PMID 32184385, 2020). "Therefore, the depression risk alleles at rs7227069 and rs1367635 consistently indicated higher DCC expression in the three selected eQTL datasets." (PMID 32184385, 2020). "We also find that DCC associating variants significantly predict depression relevant biological phenotypes, suggesting participation of this gene in the biological processes of depression pathogenesis." (PMID 32184385, 2020). "Overall, these results support the hypothesis that certain genetic variations influencing DCC expression in human brains also affect risk of depression." (PMID 32184385, 2020). "Moreover, using pathway analyses in two independent samples (n = 6455, n = 18,759), FDR-corrected associations between depression and a Netrin-1 signaling pathway were identified, comprising SNPs from multiple genes involved in Netrin-1 signaling, including DCC." (PMID 31659271, 2020). "Genes that were associated with brain volumes, depression, and schizophrenia or bipolar disorder includedAC011997.1,AKT3,BANK1,BOLL,DCC,HSPD1,HSPE1,HSPE1-MOB4,MOB4,PLCL1,RFTN2,SF3B1, andTRPS1." (PMID 40800518, 2024). "Moreover, a genome-wide investigation of differential gene expression in blood, applying a Bayesian approach, identified 165 differentially expressed genes in major depressive disorder, including overexpression of DCC." (PMID 31659271, 2020). "Therefore, our analyses using population-level expression data also supports the putative roles of DCC in synapses and brain functions, providing hints for the molecular mechanisms explaining the participation of DCC in depression pathogenesis." (PMID 32184385, 2020). "Besides, the risk alleles predict higher DCC mRNA expression in the DLPFC, which is also proven to affect depression-relevant personality traits, cognitive function and putamen volumes in independent samples." (PMID 32184385, 2020).
schizophrenia (14 papers, 2010 to 2025). A major psychotic disorder characterized by abnormalities in the perception or expression of reality. "Subsequently, a much larger genome wide association study (GWAS), applying a false discovery rate (FDR) correction, found that an intronic locus of DCC (rs4632195) is associated with schizophrenia (n = 82,315)." (PMID 31659271, 2020). "DCC is involved in the organization of dopaminergic circuits within the cortex, and several association studies have identified DCC as a promising candidate for schizophrenia." (PMID 29045412, 2017). "Thus, if the rs2229080 risk allele disrupts the LOH target site (which downregulates DCC), the authors proposed that the risk allele would result in increased DCC expression, changing mesocorticolimbic dopamine development and ultimately contributing to the schizophrenia phenotype." (PMID 31659271, 2020). "Understanding how Netrin, DCC, and LAR-RPTP family proteins act together to regulate cell-cell signaling may be important for human health, as these genes are associated with neurological disorders, such as schizophrenia, as well as cancer." (PMID 29742100, 2018). "This switch in the relative levels of DCC and UNC5H takes place during a critical developmental period marked by substantial reorganization and vulnerability of the mPFC DA system, which coincides with the onset of symptoms of many psychiatric disorders, including schizophrenia." (PMID 20628609, 2010).
breast carcinoma (12 papers, 2000 to 2025). "rs2229080 of DCC(Deleted in Colorectal Carcinoma Netrin1 Receptor) has been studied in the Chinese population concerning breast cancer and it was found that this variant has been associated with reduced breast cancer risk." (PMID 32487238, 2020). "We conducted a case-control study to investigate the impact of three DCC gene variants (rs2229080, rs7504990, and rs4078288) on breast cancer susceptibility in Chinese women." (PMID 27127179, 2016). "Previous research suggests that DCC-2036 impedes tumor growth and metastasis in breast cancer by targeting Tie-2+ macrophages, yet its specific impact on CRC’s TME requires further exploration." (PMID 39788945, 2025). "Significant correlations were found between genomic alterations of the DCC - and c-erbB-2 genes in disseminated breast cancer cells and actuarial relapse-free survival." (PMID 11104564, 2000). "Significant differences were observed between cases without metastasis or local recurrences versus those with metastasis or local recurrences, suggesting that a decrease in DCC expression might influence the prognosis of patients with breast cancer." (PMID 27127179, 2016). "One of the most frequent regions with LOH in breast cancer is 18q, and SMAD4 and DCC located at 18q21 are inactivating tumor-suppressor gene candidates." (PMID 37650999, 2023).
gastric cancer (11 papers, 2001 to 2025). A primary or metastatic malignant neoplasm involving the stomach. "Several studies have demonstrated significant association of DCC polymorphism with colorectal, esophageal, and gastric cancer risk." (PMID 26602921, 2015). "Similar to the DCC alterations in gastric cancer, our data highlight that UNC5C alterations caused by both epigenetic and genetic events were significantly associated with CIN-positive gastric cancers." (PMID 26207151, 2015). "Next, we investigated the association between DCC protein expression and genetic and epigenetic alterations in the DCC gene in 86 gastric cancer specimens." (PMID 26207151, 2015). "Our data suggest that DCC alterations caused by both epigenetic and genetic alterations were significantly associated with gastric cancers exhibiting the CIN phenotype." (PMID 26207151, 2015). "The 18q region is also known to harbor two well-known gastric cancer associated tumor suppressor genes DCC (18q21.3) and SMAD4 (18q21.1)." (PMID 20187983, 2010). "We studied mutations in 25 of the 29 DCC exons by PCR-SSCP in 17 primary gastric cancers exhibiting LOH on 18q21." (PMID 11461076, 2001). "We investigated sequence mutations and expression of DCC in primary gastric cancers." (PMID 11461076, 2001). "DCC alterations are apparent in early-stage gastric cancers, emphasizing the importance of this growth regulatory pathway in gastric carcinogenesis." (PMID 27127179, 2016). "This study investigated the molecular events responsible for the abrogation of the netrin pathway in gastric cancer and the role played by the two dependence receptors, DCC and UNC5C." (PMID 26207151, 2015). "Using this criterion, we observed DCC methylated cases in 44/98 gastric cancers (45 %) and in 9/105 normal gastric mucosa (9 %)." (PMID 26207151, 2015). "In contrast, few studies have focused on DCC gene alterations, and its genetic/epigenetic status still remains virtually unexplored in gastric cancer, partly because of the length and complexity of this gene." (PMID 26207151, 2015). "We investigated DCC methylation status in 98 gastric cancers and 105 normal gastric mucosa specimens." (PMID 26207151, 2015). "Loss of DCC gene expression was shown to be an independent prognostic factor in AML, colorectal and gastric cancer patients." (PMID 26602921, 2015). "We found that 56/98 gastric cancers (57 %) and 31/105 normal gastric mucosa specimens (29.5 %) displayed more than 1.0 % methylation in the DCC promoter." (PMID 26207151, 2015). "We found that the frequency of gastric cancers with concurrent alterations in the DCC and UNC5C genes increased in a stage-dependent manner." (PMID 26207151, 2015). "Overall, 70 % (58 of 83 informative cases) and 51 % (40 of 79 informative cases) of gastric cancers harbored either LOH or aberrant methylation in the DCC and UNC5C genes, respectively." (PMID 26207151, 2015). "A previous study reported that reduced DCC expression was observed in a total of 38 % of gastric cancers, and stage T1–T2 tumors maintained a positive DCC expression while it was abolished in T3 tumors." (PMID 26207151, 2015). "Therefore, we looked for associations between UNC5C and/or DCC defects and TNM stage in the 98 gastric cancers that were informative for both UNC5C and DCC genetic/epigenetic results." (PMID 26207151, 2015). "Among 86 gastric cancers, 46 cases (53 %) displayed reduced DCC expression." (PMID 26207151, 2015). "Our finding that dysregulation of DCC predominantly occurs in the early phase of gastric cancer whereas UNC5C alterations occur later suggests that inactivation of these receptors is not a random process but occurs in a statistically predictable, sequential manner." (PMID 26207151, 2015). "Because UNC5C and DCC both serve as dependence receptors for netrin-1, we investigated whether defects in these receptors accumulate in a systematic or stochastic manner during the progression of gastric carcinoma." (PMID 26207151, 2015).
gastric cancer (continued). "Both DCC and UNC5C were inactivated in 97 % of CIN-positive gastric cancers and in 55 % of CIN-negative gastric cancers." (PMID 26207151, 2015). "We provide previously unrecognized and novel evidence that most gastric cancers, particularly those with CIN, possess alterations in both DCC and UNC5C receptors." (PMID 26207151, 2015). "LOH on chromosome 18q21 is found in 30–71 % of gastric cancers, and DPC4 (Smad4)/DCC have been postulated to be the major targets." (PMID 26207151, 2015). "Among the 10 gastric cancer cell lines, only the GCIY cell line expressed DCC transcripts at the same level as NHLF cells, but its promoter was methylated." (PMID 26207151, 2015). "More than 5 % methylation in the DCC and UNC5C promoters were found in 45 % (44/98) and 32 % (31/98) gastric cancers, respectively, and in 9 % (9/105) and 5 % (5/105) normal gastric mucosa, respectively." (PMID 26207151, 2015). "In the present study, a series of genetic and epigenetic analyses for DCC and UNC5C were performed in a Japanese cohort of 98 sporadic gastric cancers and corresponding normal gastric mucosa specimens." (PMID 26207151, 2015). "Both DCC and UNC5C were inactivated in 97 % of CIN-positive gastric cancers and in 55 % of CIN-negative gastric cancers, and these alterations occurred through genetic and epigenetic processes." (PMID 26207151, 2015). "Of 98 gastric cancers, 15 cancers were categorized as non-informative, 25 cancers were categorized as negative for DCC alterations, and 58 cancers were categorized as positive for DCC alterations." (PMID 26207151, 2015). "In this study, we hypothesized that downregulation of DCC and UNC5C plays an important growth regulatory function in gastric tumorigenesis, which we addressed by investigating a panel of gastric cancer cell lines and clinical specimens from patients with gastric cancer." (PMID 26207151, 2015). "In this study, we found that 97 % of gastric cancers with CIN and 55 % of those without CIN showed simultaneous alterations in both DCC and UNC5C, supporting our hypothesis that inactivation of both receptors may be required in the development of gastric cancer." (PMID 26207151, 2015).
melanoma (9 papers, 2013 to 2025). A malignant, usually aggressive tumor composed of atypical, neoplastic melanocytes. "Netrin-1 encoded by NTN1 promotes the melanoma development coupled with its receptor DCC, which, in contrast, functioned as a tumor suppressor in intestinal cancer and lung metastasis by triggering cancer cell death." (PMID 37404751, 2023). "We selected chromosome 18, as it contains the tumor suppressor DCC gene, which is known to exhibit a high load of mutations only in melanoma, in contrast to low expression, loss of heterozygosity or epigenetic silencing in other tumors." (PMID 23892400, 2013). "Although the significance of DCC in melanoma remains unknown, mutations could lead to deregulation of DCC, possibly affecting the prognosis of MM." (PMID 30373548, 2018). "Additional axon guidance cues (SLIT-ROBO and netrin-DCC/UNC5) help to define the direction of melanoma cell migration through the brain parenchyma and reflect conserved developmental logic that is used in a malignant context." (PMID 41463339, 2025). "In contrast, another report described expression of both Netrin-1 and DCC in melanoma, which appeared to play a role in survival and progression of melanoma." (PMID 36361539, 2022). "By using the same pooled melanoma and NSCLC cohorts, we also discovered other mutations of the genes FAT1, COL3A1, NRAS, NARS2, DCC, and PTPRT were associated with better ICI response and outcome." (PMID 35884556, 2022). "The transmembrane protein DCC is a member of the immunoglobulin superfamily of cell adhesion molecules and functions as a tumor suppressor in several cancers, including melanoma." (PMID 35087523, 2021). "Finally, we analyze three metastases from separate body compartments of a melanoma patient and compare their inferred evolutionary patterns in a genomic region surrounding the Deleted in Colorectal Cancer (DCC) gene." (PMID 23892400, 2013). "However, netrin-1 and its receptor DCC also control the progression of melanoma, indicating that the therapeutic targeting of this signaling axis may be a viable method for melanoma treatment." (PMID 36499024, 2022). "For instance, one study showed that melanoma cells do not express Netrin-1 or DCC but express UNC5 receptors, which trigger endothelial cell repulsion." (PMID 36361539, 2022). "High-resolution proteomics and in situ hybridization have identified the presence of netrin-1 receptors (DCC and UNC5B), SLIT-ROBO proteins, and semaphorin–neuropilin complexes in brain metastases, therefore identifying a developmental map for the directed migration of melanoma cells." (PMID 41463339, 2025).
adenoma (7 papers, 1998 to 2022). A neoplasm arising from the epithelium. "Mouse knockout models of APC/DCC have shown that loss of the DCC gene in mice that have adenomas initiated by APC loss causes a bias towards highly dysplastic adenomas." (PMID 19424478, 2008). "Before turning into carcinoma, intermediate adenomas differentiate into late adenomas triggered by mutations in the SMAD4, CDC4, and DCC genes." (PMID 35709138, 2022).